IDH1 (isocitrate dehydrogenase (NADP(+)) 1)
Diseases named in the same sentence as IDH1 in open-access papers (continued):
Sharing a sentence is not in itself a finding about the gene and the disease.
glioma (continued). "According to the IDH condition, gliomas are divided into IDH-mutant (IDH1 R132 or IDH2 R172) and IDH-wild-type; 90% of GBMs (usually primary or “de novo” GBMs) are wild-type for IDH and have a poor prognosis (median OS of 1.2 years)." (PMID 33916593, 2021). "HOXB7 expression, at both mRNA and protein levels, were upregulated in glioblastoma (GBM) and isocitrate dehydrogenase 1 (IDH1) wild-type glioma tissues." (PMID 34458259, 2021). "In gliomas, IDH1 mutations decreased the intracellular GSH levels, enhanced the levels of intracellular ROS and inhibited the growth of glioma cells." (PMID 34070746, 2021). "The results demonstrated that M2 macrophages and Tregs were preferentially involved in IDH1 wild-type and higher grades gliomas." (PMID 33493139, 2021). "We used primary cultures and a new cell line to explore the influence of NOTCH1 activation and BMP treatment on the IDH1-mutant glioma cell phenotype." (PMID 33925547, 2021). "In adults, diffuse wild type (wt) IDH1 gliomas appear principally in patients over 50 years old and commonly are HGG, WHO grade IV of malignancy." (PMID 34168976, 2021). "AGI-5198 is a reversible competitive inhibitor selectively targeting the IDH1 R132H mutant enzyme, which resulted in reduced D-2-HG level, suppressed cellular proliferation, and enhanced cell differentiation in human glioma cells and mouse models." (PMID 34571995, 2021). "In gliomas, the cluster with high glycolytic activity mainly belongs to IDH1 wild-type cancer patients, as per our findings." (PMID 33627136, 2021). "Compared to IDH1/2 mutant gliomas, the IDH wild-type gliomas represent the most devastating subgroups with heterogeneous genetic background and poor outcome." (PMID 33493139, 2021). "Mutant IDH1 1p/19q-codel gliomas are usually oligodendrogliomas and frequently co-express mutations in TERT promoter (TERTp) and CIC." (PMID 34168976, 2021). "IDH1/2 mutation-induced methylation suppresses the recruitment of TAM and induces an immune response in gliomas." (PMID 34659216, 2021). "Heterozygous mutations in IDH1 and IDH2 have also been detected in gliomas/glioblastomas and acute myeloid leukemia (AML)." (PMID 34790172, 2021). "IDH1/2wt and IDH1/2mut glioma samples were matched by grade (Grade 2/3 versus Grade 4) and subsequently subjected to differential gene expression analysis." (PMID 34424450, 2021). "Further analysis of the TCGA database revealed that MCT1 expression was significantly reduced in IDH1-mutant glioma samples compared to those with wild-type IDH1." (PMID 34685601, 2021). "Related to this pathway is CD73, an enzyme shown to be preferentially expressed by tumor cells in glioma patients and upregulated in immune cells, especially in IDH1-mutant gliomas." (PMID 34440802, 2021). "Accumulation of 2-HG leads to a remarkable downregulation of B7H3 protein and the activity of IDH1-R132H mutant is responsible for B7H3 reduction in glioma cells." (PMID 34079802, 2021). "Based on that, PARP inhibition has been shown to induce temozolomide cytotoxicity on IDH1-mutant glioma cells." (PMID 34356864, 2021). "In a recent study, using organelle lipidomics and Raman spectroscopy, it was shown that membrane integrity of especially the ER and Golgi apparatus are disrupted in IDH1-mutant glioma cells because of dysregulated lipid metabolism." (PMID 34356864, 2021). "The IDH1-mutant plays an important role in glioma cell glucose induction, glutamine metabolism, lipid synthesis, and cell redox regulation." (PMID 34733261, 2021).
glioma (continued). "Independent studies using MRS/NMR show that phosphocholine (PCho) and glycerophosphocholine (GPCho) are increased in cultured glioma cells expressing mutIDH1R132H, xenograft models, and PTBs compared with equivalent WT IDH1 glioma samples." (PMID 35028610, 2021). "RTEL1 and GMEB2 were also significant eQTLs in the context of early CNS development and/or in IDH1 wild‐type glioma." (PMID 33169458, 2021). "Both IDH1/2wt and IDH1mut glioma cells responded to panobinostat with increased H3K14/18/27Ac histone marks." (PMID 34424450, 2021). "Cells from mouse PDXs of mutIDH1 glioma have been shown to have significantly higher mitochondrial density than corresponding WT IDH1 cells, an interesting observation given that IDH2 localizes to mitochondria." (PMID 35028610, 2021). "Based on isocitrate dehydrogenase (IDH) 1/2 mutation status, glioblastomas can also be defined as primary (IDH1/2 wildtype), which originate de novo and secondary (IDH1/2 mutant), which evolve from lower grade gliomas (accounting for 80% IDH1/2 mutant cases)." (PMID 33493139, 2021). "A number of mutant IDH1 inhibitors are currently being evaluated in clinical trials with glioma patients, including AG-120 (Ivosidenib), AG-881 (Vorasidenib), BAY1436032 (Bayer), and DS-1001b (NCT02746081)." (PMID 33842321, 2021). "In glioma, human IDH1-mutant gliomas have less infiltrating immune cells than IDH1 wild-type gliomas." (PMID 33493139, 2021). "Among these subtypes, point mutations in IDH1 and IDH2 have been reported in gliomas of grade II and III developed from low-grade glioma." (PMID 33562094, 2021). "WHO grade IV, SVZ involvement, tumor-SVZ distance from 0 to 10 mm, IDH1 mutation, and chemotherapy serve as independent predictors of PFS of patients with glioma." (PMID 34490090, 2021). "Heterotopic and orthotopic IDH1 mutant glioma xenografts are also utilized to model this disease state." (PMID 33806933, 2021). "Microglia in IDH1-mut gliomas expressed similar levels of HLA-DR as microglia in IDH1-wt gliomas and BrM; however, only in IDH1-wt gliomas did these cells upregulate CD14 and CD64, which is a sign of their activation." (PMID 33809675, 2021). "In general, as presented above, IDH1-mutant (mIDH1) gliomas tend to be less populated with TILs when compared to IDH1-wt tumors." (PMID 34168976, 2021). "The mutant IDH-1 reduces the conversion of α-ketoglutarate to D-2-hydroxyglutarate (D2HG), and the levels of D2HG are known to surpass 30 mM in IDH-1 mutant gliomas." (PMID 34262432, 2021). "Patients with lower-grade gliomas (grades II-III) and glioblastoma show significantly longer OS in the presence of IDH1 or IDH2 mutations." (PMID 34178638, 2021). "An MRE study also found IDH1-R132C-mutant WHO grade III gliomas to be stiffer than IDH1-wildtype ones." (PMID 34572766, 2021). "Developing robust pathophysiological models to study metabolism in mutant IDH1/2 glioma has been challenging." (PMID 35028610, 2021). "Well-studied examples include BRAF V600E in melanoma, IDH1 R132H in low-grade glioma and KRAS G12D in pancreatic and colorectal cancer." (PMID 33556087, 2021). "IDH2 mutations are mutually exclusive with IDH1 mutations, and thus far, have been found rarely (3.3%) in WHO grade II or III gliomas and much rarely (less than 1%) in GBMs." (PMID 33981605, 2021). "CEST-EPI has been shown to be effective an a non-invasive biomarker to distinguish between IDH1 mutant and wild type gliomas, and also 1p/19q codeleted from intact IDH1 mutant gliomas." (PMID 34294864, 2021).
glioma (continued). "Collectively, the results indicated that the compromise of glutaminolysis in IDH1 mutant gliomas is compensated for by increased, PC-mediated anaplerotic pyruvate flux and reduced PDC flux." (PMID 33808495, 2021). "It is noteworthy, that the role of glutamine metabolism in glioma has become more important with the discovery that glutamine can give rise to the oncometabolite 2HG in gliomas that have IDH1/2 mutants." (PMID 34944036, 2021). "In gliomas, increased hBCATc and hBCATm expression has been limited to gliomas with wild-type isocitrate dehydrogenase 1 (IDH1), cytosolic and IDH2, mitochondrial." (PMID 33367952, 2021). "In the present study, we accessed glioma patient cohorts and tissue microarray to evaluate the expression pattern of BCAT1 for determining its prognostic value and its relationship with IDH1 mutation status." (PMID 33493139, 2021). "Overexpression of mutant IDH1 in glioma cells resulted in an increase in intracellular ROS levels, showing that the mutant IDH1 affected growth inhibition by induction of cell apoptosis and inhibition of proliferation." (PMID 34070746, 2021). "Based on these alterations and the previous studies showing the efficacy of bromodomain and extraterminal motif (BET) inhibitors for primary GBMs, the authors tested BET inhibitors on IDH1-mutant glioma cells." (PMID 34356864, 2021). "To assess the effect of HDAC inhibition on glioma based on IDH1/2 status, we employed six patient-derived glioma cell lines: three IDH1/2wt (0827, 0923, 0211) and three IDH1mut (0905, BT142, TB096)." (PMID 34424450, 2021). "Earlier studies revealed widespread IDH1 mutations at Arg132, an active site of the enzyme, in WHO grade II and III (referred to as lower-grade) glioma and in WHO grade IV secondary glioblastoma." (PMID 34440884, 2021). "SUVmax on PET can predict IDH1 mutation with adequate sensitivity and specificity, as is supported by reduced glucose consumption in IDH1 mutant gliomas." (PMID 33472598, 2021). "In 2013, two companion papers indicated that 5-azacytidine and decitabine, which are well-known DNA methyltransferase inhibitors (DNMTi), induced differentiation of IDH1-mutant glioma cells and inhibited tumor growth in xenograft models." (PMID 34356864, 2021). "Given that IDH1-mutant cancers are exquisitely reliant on NAMPT for their NAD supplies (as they downregulate NAPRT expression), NAMPT inhibitors were found to exhibit remarkable antitumor activity against IDH1-mutant glioma and fibrosarcoma xenografts." (PMID 34068917, 2021). "Since an IDH1 mutation is well known to be associated with a better overall survival and response to chemotherapy treatment, such as temozolomide, compared to IDH1-wildtype glioma, this understanding could help to identify biological targets that could be exploited to improve patient outcomes." (PMID 34503108, 2021). "In MSK_Impact, IDH1 alteration was 33% in various types of gliomas and 14% in hepatobiliary cancer, whereas IDH2 mutation was seen most frequently in mature T and NK neoplasms." (PMID 34440884, 2021). "Somatic heterozygous mutations in IDH1 and IDH2 occur in up to 60% of central conventional chondrosarcoma, 80% of WHO grade II–IV glioma, 20% of intrahepatic cholangiocarcinoma and 10% of acute myeloid leukemias (AML)." (PMID 34069550, 2021). "IDH1 mutation is present in more than 70% of grade II and III gliomas and around 85% of secondary grade IV GBMs, which usually evolve from astrocytoma." (PMID 34722888, 2021). "Missense mutations in codon 132 of IDH1 or codon 172 of IDH2 are the defining molecular feature of IDH-mutant astrocytomas and are associated with the glioma CpG island methylator phenotype (G-CIMP)." (PMID 33293629, 2021). "As a single agent, 5-azacytidine had similar effects on IDH1-wildtype and -mutant glioma cells in vitro and slightly reduced IDH1-mutant tumor growth in vivo." (PMID 34356864, 2021).
glioma (continued). "Isocitrate Dehydrogenase 1/2 (IDH1 and IDH2) mutations (IDHmut) are the most common genetic alteration in glioma grade II and III and secondary glioblastoma and these mutations increase reliance on glutamine metabolism, suggesting a potential vulnerability." (PMID 33681764, 2021). "In detail, gliomas with visible 5-ALA fluorescence showed a significantly higher rate of IDH1 wildtype tumors." (PMID 34395266, 2021). "By comparing the expression of SH2B3 in the IDH1 WT and mutant groups, we observed that SH2B3 is significantly highly expressed in IDH1 WT gliomas." (PMID 33937225, 2021). "Conclusion: dMRI-derived parameters are promising biomarkers for predicting IDH1 genotype in LrGGs, and MK has shown great potential in assessing glioma cell proliferation." (PMID 34880724, 2021). "It is reported that patients with IDH1 mutant gliomas have higher global functional connectivity, which is difficult to recover even after the tumor is removed." (PMID 34220689, 2021). "IDH-mut oligodendrogliomas had the longest median OS (16.6 years), followed by IDH-mut astrocytomas (10.0 years) and IDH1-R132H-nm gliomas (3.1 years; p < 0.001 for all)." (PMID 33538917, 2021). "Isocitrate dehydrogenase 1 (IDH1) mutational status has been well recognized to be an important prognosis biomarker, and patients with IDH1 mutant gliomas commonly have a favorable prognosis compared with patients with wild-type (WT) IDH1 tumors." (PMID 33937225, 2021). "In our study, the glymphatic function of IDH1 wild-type gliomas, measured with the ALPS index, was significantly lower than that of IDH1 mutant gliomas." (PMID 34631582, 2021). "IDH1 mutation, which was found to disrupt SVZ and drive tumor progression, was detected in 53.2% of glioma population here, similar to prior studies." (PMID 34490090, 2021). "Among these features, tumor location in the frontal lobe in IDH1-mutant gliomas has been reported by many investigators in existing literature." (PMID 33553421, 2021). "In the meantime, the autophagy flux is more active with higher LC3B-II and lower p62 in IDH1-R132H glioma cells than in IDH1-WT cells." (PMID 34079802, 2021). "Splitting of the IDH1-wt glioma cohort according to the MGMT promoter methylation showed a trend toward a higher proportion of CD56int/brightCD16+ NK cells in the unmethylated cases." (PMID 34571910, 2021). "Among these molecular markers, IDH1, 1p19q, and MGMT methylation have been closely associated with the prognosis and chemotherapy sensitivity of glioma patients, although these markers have limited sensitivity and accuracy." (PMID 34876094, 2021). "They observed high sensitivity of patient-derived IDH1-mutant glioma cells with submicromolar IC50 values, which are several orders of magnitude lower than IC50 of temozolomide." (PMID 34356864, 2021). "The distribution difference was significant indicating that IDH1 wide type gliomas patients were more likely to be diagnosed as HGG." (PMID 33795525, 2021). "Certain genetic alterations are currently used in glioma classification and survival prognostication, such as 1p/19q co-deletion, ATRX and IDH1/2 mutations." (PMID 34341417, 2021). "Silico analysis and western blot confirmed that HK1 and PKM2 in IDH1 wild-type gliomas were significantly higher than in IDH1 mutant group, while PC was significantly higher in IDH1 mutant gliomas." (PMID 33472598, 2021). "In this study, we showed that cultured IDH1mut glioma cells are more sensitive than IDH1/2wt cells to the FDA-approved pan-HDACi, panobinostat, and that this is mediated through both cytotoxic and cytostatic effects." (PMID 34424450, 2021).
glioma (continued). "Based on this finding, the same group recently demonstrated that boosting these pathways via the addition of N,N-dimethylsphingosine (NDMS) and sphingosine C17 induced an apoptotic response in IDH1-mutant glioma cells." (PMID 34356864, 2021). "In our study, we observed a small subset (27/427) of IDH1 mutant gliomas with a high degree of TMEFF2 methylation that exhibited a poor prognosis compared to the large subset (400/427), which had less TMEFF2 methylation." (PMID 33663520, 2021). "Tumors were divided into three groups: lower grade glioma (IDH1-mutant diffuse astrocytoma and IDH1-mutant anaplastic astrocytoma), higher grade glioma (IDH1-wildtype diffuse astrocytoma and IDH1-wildtype anaplastic astrocytoma), and glioblastoma." (PMID 34743250, 2021). "The proper function of glutaminase would be an important factor between the IDH1/2 mutational status and the WHO grade classification of gliomas." (PMID 34490096, 2021). "Glioma cells in PpIX hotspots were IDH1 mutant and expressed nestin suggesting they had acquired stem-like properties." (PMID 33959713, 2021). "IDH1 mutant glioma tissues (n = 23) harboured lower TMEFF2 methylation levels than IDH1 wild-type glioma tissues (n = 20) (P < 0.05)." (PMID 33663520, 2021). "WHO grade II and grade III IDH1 mutant gliomas were diagnosed in 269 (62.1%) and 164 (37.9%) patients, respectively." (PMID 33669525, 2021). "In 2016, the revision of the WHO classification of CNS tumors has highlighted the importance of the IDH1 or IDH2 mutation and co-deletion of chromosomal arms 1p and 19q for the diagnosis of gliomas." (PMID 33493139, 2021). "They found that grade III or IDH1 wild type gliomas had both higher immune and stromal scores.They also found that ESTIMATE algorithms‐based scores were meaningful in subtype classification of glioblastomas and affected prognosis." (PMID 33898320, 2021). "A recent study by others suggested that IDH1mut gliomas were actually more resistant to HDACi; however, that study used overexpression of IDH1 R132H in U87MG and U373MG glioblastoma cells." (PMID 34424450, 2021). "These advances collectively demonstrate that the IDH1 and IDH2 mutations play a key role in the therapeutic determination of gliomas and a subset of other malignancies." (PMID 35996504, 2021). "In recent years, since the discovery of IDH1/2 mutation prevalence and its prognostic role in LGG, glioma classification has moved from histopathological features towards molecular characteristics." (PMID 34771529, 2021). "Highly reliable antibodies for IDH1 R132H, which constitutes approximately 90% of all IDH mutations in gliomas, are commercially available and widely used, but antibodies for other IDH1 and IDH2 mutant proteins are less widely available." (PMID 34829476, 2021). "Glioma cells harboring mutIDH1 appear to be less glycolytic and rely on oxidative phosphorylation to a greater extent than WT IDH1 glioma cells." (PMID 35028610, 2021). "Similar to IDH1 mutation, 5hmC can be a proper biomarker for distinguishing patients with GBM from gliomas, indicating the potential utility of 5hmC in gliomas screening." (PMID 34603383, 2021). "Our findings reveal the relationship between dMRI parameters and IDH1 genotype and proliferation index in gliomas." (PMID 34880724, 2021). "In gliomas, 2HG, which is a competitive inhibitor of multiple α-KG-dependent dioxygenases, produced by mutant-IDH1, has been found to inhibit BCAT1 and BCAT2." (PMID 33367952, 2021). "They found that these combined modalities were able to differentiate glioma grade (AUC 0.852), ATRX mutation (AUC 0.851), MGMT mutation (AUC 0.757), IDH1 mutation (AUC 0.887), and 1p19q codeletion (AUC 0.978)." (PMID 34194287, 2021).